OR2G3 (olfactory receptor family 2 subfamily G member 3)
Description:
Odorant receptor.
Synonyms: OR1-33
Tractability: Antibody: UniProt places it where antibodies can reach, with medium confidence; UniProt predicts a signal peptide or a membrane-spanning region; its Gene Ontology location is reachable by antibodies, with medium confidence.
Gene: Protein-coding gene on chromosome 1 (247,605,586 to 247,606,515, forward strand). Ensembl gene ENSG00000177476.
Subcellular location: Cell membrane
Pathways (Reactome):
Sensory Perception: Expression and translocation of olfactory receptors
Gene Ontology:
Molecular function: olfactory receptor activity; G protein-coupled receptor activity
Biological process: detection of chemical stimulus involved in sensory perception of smell; G protein-coupled receptor signaling pathway
Cellular component: plasma membrane; membrane
Genetic constraint (gnomAD): Loss-of-function variants: 0 observed, 0.17 expected, observed/expected ratio (o/e) 0, 90% interval 0 to 1.88. That is too few expected variants to judge how well the gene tolerates losing a copy. Missense variants: 374 observed, 381.05 expected, observed/expected ratio (o/e) 0.98, 90% interval 0.9 to 1.07. Synonymous variants: 152 observed, 150.38 expected, observed/expected ratio (o/e) 1.01, 90% interval 0.88 to 1.16.
Homologues: Orthologues: chimpanzee OR2G3 (98% identical), pig OR2G3 (90% identical), rabbit OR2G3 (83% identical), guinea pig OR2G3 (75% identical). Paralogues in human: OR2G6 (64% identical), OR2G2 (62% identical), OR2C1 (60% identical), OR2H1 (60% identical), OR2B2 (60% identical), OR2H2 (60% identical), OR2W1 (60% identical), OR2Y1 (60% identical), OR2C3 (59% identical), OR2B6 (59% identical), OR2J2 (58% identical), OR2B11 (58% identical), and 80 more.